CD47 (CD47 molecule)
Diseases named in the same sentence as CD47 in open-access papers (continued):
Sharing a sentence is not in itself a finding about the gene and the disease.
atherosclerosis (continued). "suggest that CD47 signaling in myeloid cells such as macrophages may have a protective role against atherosclerosis in vivo, and that systemic CD47 inhibition may reduce atherosclerosis by suppressing smooth muscle cell CD47 expression and stimulating efferocytosis." (PMID 40821806, 2025). "Anti-CD47 treatment reduces vascular inflammation in human patients and ameliorates atherosclerosis in hypercholesterolemic ApoE−/− mice by correcting defects in efferocytosis and normalizing the clearance of diseased vascular tissue, leading to the regression of atherosclerosis." (PMID 39926714, 2024). "CD47 Ab blockade could reverse malignant cell resistance to programmed cell removal (PrCR), allowing the clearance of diseased vascular tissue and promoting its normalization to ameliorate atherosclerosis." (PMID 38398223, 2024). "Additionally, blocking CD47 reestablishes efferocytosis of these SMCs and prevents atherosclerosis." (PMID 33854480, 2021). "The study of the CD47 signaling pathway may provide new ideas for regulating the progression of atherosclerosis, delay the progression of atherosclerosis, and thus improve the treatment and intervention of vascular diseases such as stroke, as reducing the incidence of strokes is a top priority." (PMID 32733941, 2020). "Further, since we anticipate that the major function of activated DCs is activation of T cells, but T cell depletion did not abrogate increased lesion size, we propose that DC activation is not a cause for the increased atherosclerosis observed in Cd47−/− mice." (PMID 31337788, 2019). "Molecules like CD47 that present a “don’t eat me” signal to the cells that clear apoptotic debris have been shown to be expressed in murine and human atherosclerotic plaques, and inhibition of CD47 stimulates efferocytosis and reduces atherosclerosis in murine models." (PMID 31448091, 2019). "Inhibitors of the CD47-SIRPα signaling axis, such as CD47 monoclonal antibodies and SHP1 inhibitors, can enhance macrophage efferocytosis in atherosclerosis, alleviating plaque inflammation and improving the condition of atherosclerosis." (PMID 41035425, 2026). "In atherosclerosis, its therapeutic relevance primarily lies in the inhibition of TSP1-induced CD47 activation." (PMID 41300494, 2025). "Furthermore, statins have been found to downgrade the expression of integrin-associated protein [cluster of differentiation 47 (CD47)], a key player in immune evasion, by disrupting the “do not eat me” signal to macrophage-mediated phagocytosis in atherosclerosis therapy." (PMID 40040956, 2025). "In an atherosclerosis model established in ApoE−/− mice, PMSN encapsulating anti-CD47 antibody delivery significantly promoted the efferocytosis of necrotic cells in plaques." (PMID 35118420, 2022). "Mouse treated with a combination of anti-CD47 and anti-TNF-α antibodies showed a better reduction in atherosclerosis than anti-CD47 alone." (PMID 36359349, 2022). "CD47 antibody B6H12 downregulates VEGFR2 and SHP-2 phosphorylation and CD47 binds SIRPα and TSP-1 to regulate the expression of VEGF and VEGFR2, thereby affecting the progression of atherosclerosis." (PMID 32733941, 2020). "Therefore, the TSP-1/CD47/VEGF/VEGFR2 signal may have an important influence on atherosclerosis." (PMID 32733941, 2020). "TSP-1 is a factor that has been found to have an antiangiogenic effect, and CD47, as the receptor of TSP-1, can participate in the regulation of antiangiogenesis of atherosclerosis." (PMID 32733941, 2020). "WT or Cd47−/− mice (n = 16–17/group) were injected with a single-dose of AAV-PCSK9DY at 10 weeks of age and fed HCD for 10 weeks before assessment of atherosclerosis." (PMID 31337788, 2019). "Importantly, anti-CD47 mAb treatment did not mimic the effect of CD47-deficiency on NK phenotype, which is in line with anti-CD47 mAb treatment and CD47-deficiency having divergent effects on atherosclerosis." (PMID 31337788, 2019).
atherosclerosis (continued). "Reducing the “do not eat me” signal is a new strategy for atherosclerosis treatment, with some drugs already researched or approved for clearing ACs, such as CD47 antibodies and PD1-/PD-L1 antibodies." (PMID 41293421, 2025). "Summary of mouse models of atherosclerosis induced by LAG-3, TIM-3, and CD47 pathway inhibition." (PMID 40821806, 2025). "Studies in vitro showed that TSP-1 inhibits lymphangiogenesis via activation of CD47 in Lymphatic Endothelial Cells (LEC), which suggests that LEC CD47 could, in the future, be a potential therapeutic target in the treatment of atherosclerosis." (PMID 41010873, 2025). "Similarly to atherosclerosis, acute coronary syndrome (ACS) that arises from myocardial injury exhibits abnormally elevated levels of CD47." (PMID 41590849, 2025). "In pathological states such as atherosclerosis, myocardial infarction, ischemia–reperfusion injury (IRI), pulmonary hypertension, and heart failure, CD47 is frequently upregulated, thereby impairing efferocytosis, sustaining inflammation, and limiting reparative angiogenesis." (PMID 41303525, 2025). "The CD47 inhibitor BRB-002 has shown dose-dependent anti-AS effects in Apoe-/- mouse models, holding promise for achieving dual therapeutic effects in both cancer and atherosclerosis in further clinical trials." (PMID 40821806, 2025). "In this review, we focus on CD47 and its role in non-neoplastic diseases, including neurological disorders, atherosclerosis and autoimmune diseases." (PMID 38125492, 2023). "CD47−/− can trigger T cell activation, but the activation of T cells will not promote atherosclerosis because T cell activation in CD47−/− mice does not produce more TNF-α compared with the wild type." (PMID 32733941, 2020). "Recent studies have shown that CD47 plays a role in atherosclerosis not through “cell aggregation” but through the dysregulation and activation of NK cells." (PMID 32733941, 2020). "Therefore, our study provides new insights into the molecular function of the MIAT/miR-149-5p/CD47 signaling pathway in the pathogenesis of plaque vulnerability and highlights the potential of MIAT as a new therapeutic target for atherosclerosis." (PMID 30755588, 2019). "During the preparation of this manuscript the role of CD47 in atherosclerosis was not known." (PMID 31337788, 2019). "Furthermore, if efferocytosis was augmented in Cd47−/− mice, the expected outcome would be a reduction in atherosclerosis rather than an increase, as efferocytosis has repeatedly been shown to reduce atherosclerotic lesion formation." (PMID 31337788, 2019).
Thrombocytopenia (56 papers, 2009 to 2025). A reduction in the number of circulating thrombocytes. "It is anticipated that using anti-SIRPα to target the SIRPα/CD47 axis may have a beneficial safety profile due to SIRPα’s more constrained expression, which can lower the risk of adverse events such as acute anemia, thrombocytopenia caused by anti-CD47." (PMID 37345054, 2023). "However, lack of CD47 on platelets also results in very rapid clearance when transfused into wild-type recipients, and both CD47-deficient mice and SIRPα-mutant mice have a mild spontaneous antibody-independent thrombocytopenia." (PMID 23401787, 2013). "For example, when anti-CD47 antibodies are used to inhibit the interaction between CD47 on CTCs and SIRPα on neutrophils, thereby enhancing neutrophil phagocytosis of CTCs, free anti-CD47 antibodies lack specificity and may cause limitations such as red blood cell toxicity and thrombocytopenia." (PMID 40528159, 2025). "Compared with SIRPα-Fc fusion proteins, an anti-SIRPα antibody, such as BMS-986351, provides a higher-affinity blocking capability to CD47, has single-agent activity, and has shown minimal impact on hematologic parameters, including thrombocytopenia." (PMID 38319147, 2024). "As expected from the physiology of CD47 expression, hematologic changes were the most common grade 3 or higher TRAEs; neutropenia (6.5%) and thrombocytopenia (8.3%) were the most common in anti-CD47 mAbs and selective SIRPα blockers, respectively." (PMID 36439116, 2022). "Thrombocytopenia was postulated as an on‐target effect of CD47 blocking together with opsonisation by activating IgG1, resulting in platelet removal by macrophages." (PMID 35908284, 2022). "A high dose of CD47 blockade might deliver better efficacy, but it could cause RBC and platelet depletion toxicities, resulting in severe hemolysis and thrombocytopenia." (PMID 39335665, 2024). "However, the current low responsiveness of oncology patients to CD47 monotherapy and its severe post-treatment adverse effects, such as hemolysis and thrombocytopenia, limit the therapeutic efficacy of CD47." (PMID 38398223, 2024). "However, given that acquired resistance and adverse events (e.g., acute anemia and thrombocytopenia) have been observed in systemic CD47/CD24 antibody administration, the feasibility of blocking CD47/CD24 alone or in combination in GBM remains uncertain." (PMID 37474548, 2023). "As adverse events of anti-CD47 mAbs, many CD47+ cells, such as erythrocytes and platelets, may be less protected against phagocytosis, leading to hemagglutination, acute anemia, and thrombocytopenia." (PMID 35886899, 2022). "It has been hypothesized that these antibodies could be more specific for neoplastic cells and avoid side effects such as hemolytic anemia or thrombocytopenia that result from the relatively high expression of CD47 on red blood cells and platelets." (PMID 32677994, 2020). "In addition, CD47-deficient mice are severely sensitive to experimental autoimmune hemolytic anemia (AIHA) and experimental thrombocytopenia." (PMID 23401787, 2013). "Thus, agents targeting CD47 may bind to erythrocytes or platelets and the subsequent phagocytosis could induce hematologic toxicity such as hemolytic anemia and thrombocytopenia." (PMID 35422796, 2022). "Notably, CD47-targeting agents (i.e., Hu5F9-G4 and TTI-621) could cause acute anemia and thrombocytopenia in people, which might as well as depend upon the Fc format." (PMID 34305918, 2021). "Although several CD47-targeting agents are currently in phase I clinical trials and demonstrate activity in combination therapy, high and frequent dosing was required and safety signals (acute anemia, thrombocytopenia) were recorded frequently as adverse events." (PMID 31801627, 2019). "Indeed, it has been observed that CD47-targeting agents (i.e. Hu5F9-G4, TTI-621) induce acute anemia and thrombocytopenia in patients which may also further depend on the Fc format." (PMID 31801627, 2019).
colon carcinoma (53 papers, 2009 to 2026). "In our study, we observed differences in the expression levels of various immune checkpoint molecules, including PDCD1, CD86, and CD47, between the high and low-risk groups, indicating that colon cancer patients in the two risk groups may exhibit different responses to ICIs." (PMID 38188686, 2023). "For example, lentiviral transfection was used to overexpress CD47 in CT26 colon carcinoma cells, generating exosomes with prolonged circulation time and enhancing tumor targeting through the CD47-SIRPα pathway." (PMID 41551981, 2026). "Studies have found that using blocking antibodies targeting CD47 overexpressed on colon cancer cells and SIRPα on TAMs can inhibit the migration of colon cancer cells." (PMID 40873588, 2025). "In vivo, NILK-2401 significantly delayed tumor growth in a NOD-SCID colon cancer model and a syngeneic mouse model using human CD47/human SIRPα transgenic mice and prolonged survival." (PMID 38720892, 2024). "This study used organoids to examine the efficacy of CD47‐SIRPα inhibitors on the immune microenvironment of colon cancer." (PMID 39309690, 2024). "Through a series of experiments, the authors showed that inhibiting SHP2 activity in colon cancer cells reduced CD47 expression and increased phagocytosis by immune cells." (PMID 37465677, 2023). "When evaluated using TCGA and GTEx datasets, we observed that CD47 expression was markedly higher in colon cancer contrasted with healthy counterparts, while SIRPα expression was not different." (PMID 37291116, 2023). "The robust immunogenicity of bacterial lysate cooperates with anti-CD47 nanobody to activate both innate and adaptive immune responses, generating robust antitumor effects against not only orthotopic colon tumors but also distal tumors in female mice." (PMID 36959204, 2023). "It was thus supposed that the gut microbiota mediated the anticancer responses of anti-CD47 immunotherapy in colon carcinoma-bearing mice." (PMID 36726985, 2022). "M2 macrophages express higher levels of SIRPα than M1 macrophages, and M2 macrophage-secreted IL-8 has been shown to increase CD47 expression on disseminated colon cancer cells, thereby preventing their phagocytosis." (PMID 34603322, 2021). "As anticipated, the ubiquitylation level of ENO1 was distinctly decreased in CD47-overexpressed HT29 colon cancer cells but increased in CD47-knockdown HT29 cells." (PMID 32226539, 2020). "Inhibition of CD47 with blocking antibodies or siRNA transfection obviously inhibited the migration of colon cancer SW480 cells in the presence of M2 macrophages." (PMID 32314789, 2020). "By synergistic action with inflammatory mediators, CD47 enhanced the migration capacity of colon tumor cells and promoted colon cancer development." (PMID 32984001, 2020). "Third, other studies have shown that there is an extensive crosstalk between colon cancer cells and macrophages and that CD47 promotes tumor cell migration." (PMID 26674012, 2015). "This represents a novel role for CD47 and reveals a potential role of this plasma membrane protein as a therapeutic target in the treatment of inflammatory bowel disease and colon cancer progression." (PMID 19636412, 2009). "Interestingly, under hypoxic conditions, TAMs showed decreased SIRPα expression accompanied by increased phagocytic activity, whereas colon cancer cells showed elevated expression of CD47 and exhibited greater invasiveness." (PMID 40873588, 2025). "Moreover, PEG2000‐SiNcTI‐Ph/CpG‐ZIF‐8@CM evades immune surveillance to target CT26 colon tumors in mice mediated by CD47/signal regulatory proteins α (SIRPα) interaction and PD‐1/programmed death ligand 1 (PD‐L1) interaction, respectively." (PMID 38728587, 2024). "It was used to treat the CD47+ CT26.WT syngeneic colon tumor model." (PMID 37049910, 2023).
colon carcinoma (continued). "The present study is focused on determining whether berberine, an isoquinoline quaternary alkaloid, is able to induce selective ICD in colon cancer cells in vitro while conserving the principal characteristics of CD47-mediated cell death." (PMID 38275991, 2023). "Additionally, they found that the enzyme SHP2 plays a role in regulating CD47 expression and function in colon cancer cells." (PMID 37465677, 2023). "This suggests that targeting the CD47/SIRPα axis may be a potential therapeutic strategy for colon cancer immunotherapy." (PMID 37465677, 2023). "We verified that BoxA promotes UPR, DAMPs release, and CD47 surface depletion in several mouse and human tumor cell lines; most importantly, BoxA induces tumor rejection and immunization also in mice inoculated with colon carcinoma CT26 cells." (PMID 33956406, 2021). "For the first time, we described that, in colon cancer, hypoxia impacts the SIRPα/CD47 axis through the decrease of macrophage SIRPα expression, which may favor their phagocytic capacity." (PMID 32231135, 2020). "Anti-SIRPα antibody treatment leads to enhanced macrophage phagocytic activity and reduced tumor progression in a mouse model of colon cancer and CD47-SIRPα signaling promotes the expansion and metastasis of colon cancer cells in tumor microenvironments that are rich in tumor-associated macrophages." (PMID 32082311, 2020). "Therefore, it can be hypothesized that the regulation of the CD47-SIRPα axis in colon cancer may be affected by hypoxia." (PMID 40873588, 2025). "Thus, we evaluated SIRPα and CD47 expression in human colon cancer." (PMID 37291116, 2023). "By loading siRNA targeting the immune checkpoint CD47 gene, the DMPLAC/siCD47 complex strongly suppressed the growth of multiple colon cancer models through local administration with high safety." (PMID 40006507, 2025). "Targeting phagocytosis checkpoints such as CD47-SIRPα, CD24-Siglec-10, MHC-LILRB1, PD1-PDL1 and thereby modulating immune escape in colon cancer cells has also been demonstrated." (PMID 40873588, 2025). "In syngeneic immunocompetent models of colon cancer (CT26 and MC-38), anti-CD47 was synergistic with anti-PD1 or anti-PDL1 therapy." (PMID 37468567, 2023). "Consistent with previous reports in the public database The Cancer Genome Atlas (TCGA), CD47 and PVR expressed at high levels in Esophageal Cancer (ESCA), Colon Cancer (COAD), Head and Neck Cancer (HNSC), and Stomach Cancer (STAD) analyzed by the online tool TIMER." (PMID 34068552, 2021). "The antitumor activity by CD47 blockade enhances cancer cell clearance by both of phagocytes and T cells 26, 37, and anti-CD47 antibody enhances CD8+ T cells killing but not CD4+ T cell in colon cancer cells." (PMID 34512146, 2021). "To identify mechanisms exploited by cancer cells against PrCR beyond CD47 upregulation, we first knocked out CD47 expression in SW620, a human colon cancer line, by transducing the cells with TALEN (transcription activator-like effector nucleases) plasmids and sorting for CD47 negative cells." (PMID 33603751, 2020). "To investigate the significance of CD47‐SIRPα interactions in macrophage action against gastroenterological tumors, we induced lentiviral‐mediated CD47 protein expression knockdown in Hepa1‐6 hepatoma and CMT93 colon carcinoma cells originating from B6 mice." (PMID 30460349, 2018). "Colon carcinoma-bearing mice nonresponders to anti-CD47 immunotherapy could recapitulate the response observed in mice responders after cohousing." (PMID 36726985, 2022). "CD47-SIRPα blockade by anti-CD47 antibody enhances antigen cross-presentation by DCs and promotes T cell priming, consequently, CD8+ T cells, but not CD4+ T cells, mediate killing on colon cancer cells." (PMID 34512146, 2021).